HMGB1 (high mobility group box 1)
Diseases named in the same sentence as HMGB1 in open-access papers (continued):
Sharing a sentence is not in itself a finding about the gene and the disease.
vitiligo (continued). "Investigating the effects of HMGB1 on melanocytes may be valuable for enhancing our understanding of vitiligo and developing new therapeutics." (PMID 37298700, 2023). "Among these alarmins, HMGB1 and S100B have been reported to be involved in the pathogenesis of vitiligo and could even serve as potential therapeutic targets for vitiligo." (PMID 36569840, 2022). "Additionally, HMGB1 promoted DC maturation in patients with vitiligo, contributing to oxidative stress-induced autoimmunity during the condition." (PMID 36154894, 2022). "Therefore, the elevated serum levels of HMGB1 indicate a hyperactive immune state in patients with vitiligo." (PMID 36569840, 2022). "In short, HMGB1 worsens vitiligo by impacting melanocyte survival." (PMID 36154894, 2022). "For vitiligo diagnosis, S100B had the highest sensitivity (92.31%), whereas HMGB1 had the highest specificity (85.71%); the combination of IL-1α, S100B, S100A9, and HMGB1 increased the AUC value to 0.925, with a sensitivity of 87.50% and a specificity of 85.71%." (PMID 36569840, 2022). "Therefore, FA is of promising potential in inhibiting oxidative stress-induced inflammatory response mediated by HMGB1 in vitiligo." (PMID 34917229, 2021). "Here we show that NK and ILCs from vitiligo patients produce higher amount of IFNγ under oxidative stress but also under the stimulation of the two main DAMPs implicated in vitiligo pathophysiology, namely HSP70 and HMGB1 compared to healthy subjects." (PMID 31097717, 2019). "Thus, we reproduced the experiment with NK and total ILCs from PBMC of healthy (C) and vitiligo (V) patients and this time examined their IFNγ responses after stimulation with HMGB1 or HSP70." (PMID 31097717, 2019). "Beyond this previous report, our study showed that FA dramatically reduced the mRNA level, protein level, and secretion level of HMGB1 in H2O2-treated melanocytes, implicating that FA could inhibit oxidative stress-triggered cutaneous inflammation mediated by HMGB1 in vitiligo." (PMID 34917229, 2021). "Additionally, HMGB1 could bind free DNA and HMGB1-DNA complexes and induce maturation of vitiligo patients’ dendritic cells (DC), as well as the production of cytokines and chemokines by keratinocytes." (PMID 33936032, 2021). "Oxidative stress triggered autocrine HMGB1 translocation and release from melanocytes, leading to suppression of the expression of Nrf2 and downstream antioxidant genes to induce melanocyte apoptosis, and thereby participate in the pathological process of vitiligo." (PMID 30338917, 2018). "IL-1β, HMGB1, IL-8, and IL-6 TNF-α are believed to have a crucial role in the innate immune response, and their levels were considerably increased in vitiligo patients' serum and skin." (PMID 36920542, 2023). "Extracellular disulfide-HMGB1 binds to these receptors and induces DC maturation and activation, which activates melanocyte antigen-specific CD8+ T cells and thus initiates an autoimmune response in patients with vitiligo." (PMID 40308590, 2025). "Indeed, several DAMPs [e.g., high-mobility group box 1 (HMGB1), S100B, heat-shock protein 70 (HSP70)] are increased in progressive vitiligo." (PMID 39274437, 2024). "With the dual guarantee of multivariate logistic regression and ROC analysis, we found that serum HMGB1, S100B, and S100A9 can efficiently discriminate between patients with stable and active vitiligo, and can be used as potential biomarkers for the prediction of disease activity." (PMID 36569840, 2022). "The High-mobility group protein B1 (HMGB1), as a pro-inflammation factor in the downstream of NLRP3 inflammasome, has been proved to facilitate the secretion of IL-8 and CXCL16 in keratinocytes which contributed remarkably to the pathogenesis of vitiligo." (PMID 32754591, 2020).
vitiligo (continued). "Similar to the results obtained following H2O2 stimulation, HMGB1- and HSP70-induced IFNγ production by NK and ILCs were dose- and time-dependent and responses from vitiligo melanocytes were significantly higher compared to responses in melanocytes from healthy individuals at the same dose." (PMID 31097717, 2019). "More importantly, HMGB1 activates NF-κB signalling and then promotes the production of chemokines, including CXC chemokine ligand 16 (CXCL16) and interleukin-8 (IL-8), thereby inducing CD8+ T cell migration and establishing an immune microenvironment unique to vitiligo." (PMID 40308590, 2025). "Therefore, in this study we would like to detect the serum expression of these alarmins (HMGB1, S100B, IL-1α, IL-33, S100A9, and S100A12) in NSV patients and healthy controls, to further investigate their clinical significance in the diagnosis and assessment of disease activity/severity in vitiligo." (PMID 36569840, 2022).
fibrosis (14 papers, 2013 to 2025). the formation of excess fibrous connective tissue in an organ or tissue in a reparative or reactive process. "Fibrosis progression was associated with higher HMGB1 and lower percentage nadir CD4+ T-cell count, highlighting the importance of early initiation of HBV-active ART." (PMID 38518655, 2024). "Fibrosis progression was associated with elevated HMGB1 and lower nadir CD4+ T-cell count." (PMID 38518655, 2024). "Next, to clarify which immune cells are associated with the HMGB1 and α2AP production that occurs with the development of fibrosis, we examined the effects of T and B cells on belomycin-induced dermal fibrosis using T and B cell-deficient severe combined immune deficiency (SCID) mice." (PMID 32272967, 2020). "Myocardial fibrosis was further worsened in the LPS group compared to the AF group, indicating HMGB1-mediated enhancement of fibrosis (p < 0.05)." (PMID 40989585, 2025). "Some studies have shown that HMGB1 exists in the early stage of pulmonary inflammation and late fibrosis, and glycyrrhizic acid inhibits the expression of HMGB1, which limits the progress of pulmonary toxicity." (PMID 35886594, 2022). "In this study, we showed that HMGB1 peptide effectively attenuated liver damage and promoted the regression of fibrosis in a CCl4-induced cirrhosis model in mice." (PMID 34565478, 2021). "HMGB1 is involved in innate and specific immune responses and contributes to acute lung injury in bleomycin-induced fibrosis in mice." (PMID 23402370, 2013). "Therefore, we suggest that increased HMGB1 levels in keloid may account for the abnormal dermal fibrosis." (PMID 29849053, 2018). "Since High mobility group box 1 protein (HMGB1) is overexpressed in IPF lungs and its antibody mediated neutralization exacerbates BLM-induced fibrosis, role of HMGB1 has been also suggested in PF as a DAMP which eventually stimulates TLR2 and TLR4 in PF." (PMID 41472725, 2025). "Our previous published data demonstrated that HMGB1 was up-regulated in heart tissue or serum in experimental autoimmune myocarditis (EAM); HMGB1 blockade could ameliorate cardiac fibrosis at the last stage of EAM." (PMID 24912759, 2014). "However, our data clearly showed that this HMGB1 peptide is effective for liver cirrhosis model mouse, and up to now, there is no approved anti-fibrosis drug." (PMID 34565478, 2021). "Interestingly, we found that HMGB1, a key DAMP for amplifying both inflammation and necrosis, was elevated in both animal fibrosis models, whereas it decreased after LM49 treatment, suggesting that it may serve as a collective target gene for LM49 to mediate necroinflammation." (PMID 39566909, 2025).
gastric adenocarcinoma (14 papers, 2010 to 2025). "High mobility group box 1 (HMGB1) is expressed in many tumor types including gastric adenocarcinomas and its over expression has become a known hallmark of cancer." (PMID 36359780, 2022). "Furthermore, the survival analysis showed that HMGB1 overexpression positively associated with the cancer-free survival of patients with resectable gastric adenocarcinoma." (PMID 20579387, 2010). "Furthermore, HMGB1 overexpression positively associated with cancer-free survival of resectable gastric adenocarcinomas (P = 0.023)." (PMID 20579387, 2010). "HMGB1 immunostaining was unrelated to parameters of cancer aggressiveness in pancreatic and gastric adenocarcinomas, seminomas, as well as in endometrioid endometrial carcinomas." (PMID 40804938, 2025). "Although serum levels of HMGB1 have been shown to be a useful marker to predict poor prognosis in GC, another study reported that overexpression of HMGB1 was positively correlated with cancer-free survival of resectable gastric adenocarcinomas." (PMID 23866030, 2013). "In gastric adenocarcinoma cells, the expression of HMGB1 protein was also mainly detected in the nucleus." (PMID 20579387, 2010). "In the present study, the expression of HMGB1 was detected in most of the gastric adenocarcinoma samples, as well as the borderline and normal epithelial cells." (PMID 20579387, 2010). "HMGB1 overexpression was an independent predictor of cancer-free survival for patients with resectable gastric adenocarcinomas." (PMID 20579387, 2010). "But it was confirmed that gastric adenocarcinoma showed a high rate of HMGB1 overexpression (total expression score ≥ 9)." (PMID 20579387, 2010). "In the present study, HMGB1 overexpression and its correlation with the clinicopathologic characteristics and recurrence-free survival were evaluated in gastric adenocarcinomas." (PMID 20579387, 2010). "In conclusion, the high-level expression of HMGB1 protein was detected in gastric adenocarcinoma cells." (PMID 20579387, 2010). "The overexpression of HMGB1 protein indicates that HMGB1 may play a role in the tumorigenesis of gastric adenocarcinomas." (PMID 20579387, 2010). "In many gastric adenocarcinomas, the overexpression of HMGB1 was found." (PMID 20579387, 2010). "And the overexpression of HMGB1 may be a marker of good prognosis of gastric adenocarcinoma given curative resection combined with adjuvant chemotherapy." (PMID 20579387, 2010). "Almost all the gastric adenocarcinomas showed HMGB1 positive staining mainly in the nucleus, and the overexpression of HMGB1 was found in cancerous tissues with higher strong reactivity rate, compared with non-cancerous tissues (total expression score ≥ 9, 42.0% vs. 9.0%, P < 0.001)." (PMID 20579387, 2010). "But the rate of HMGB1 overexpression (total expression score ≥ 9) was elevated in gastric adenocarcinoma cells, compared with corresponding non-cancerous cells (41.0% vs. 9.0%, P < 0.001)." (PMID 20579387, 2010). "In the present study, the expression of HMGB1 protein was evaluated with tissue microarray(TMA) and immunohistochemical(IHC) staining procedures to study the prognostic significance of HMGB1 and its correlation with the clinical and histopathologic features of resectable gastric adenocarcinomas." (PMID 20579387, 2010). "The expression of high mobility group box 1 (HMGB1), a novel inflammatory molecule, is increased in the gastric adenocarcinoma tissues compared with that in adjacent non-cancer tissues, and correlates with the metastasis." (PMID 28350359, 2017).
infarction (14 papers, 2007 to 2025). A localised pathological necrosis of tissue resulting from obstruction of the blood supply usually by a thrombus, an embolus, or vascular torsion. "HMGB1 levels gradually decreased in the infarction core, with a significant reduction observed 24 h post-PTS." (PMID 39910417, 2025). "The concurrent attenuation of both parameters following anti-HMGB1 treatment underscores its potential in limiting post-infarction structural damage through modulation of inflammation and oxidative pathways." (PMID 41291022, 2025). "The IL6/ADPN/HMGB1 loop between adipocytes and macrophages in the border zone contributes to different clinical outcomes post-infarction." (PMID 38601146, 2024). "The level of VEGF-A mRNA expression in the peri-infarction area was significantly higher in the HMGB1 group than in the control (1.63 ± 0.64 vs. 1.18 ± 0.25, P = 0.029)." (PMID 32275672, 2020). "Systemic administration of the HMGB1 fragment induces angiogenesis and reduces fibrosis by mobilizing BM-MSCs to the peri-infarction area, thereby providing a potential new approach for the treatment of ICM with CHF." (PMID 32275672, 2020). "Capillary density at the peri-infarction area was significantly greater in the HMGB1 group (1797.98 ± 271.85 vs. 959.04 ± 143.40/mm2, P < 0.0001) than in the control." (PMID 32275672, 2020). "For cardiomyocyte hypertrophy at the peri-infarction area, cardiomyocyte size was significantly smaller in the HMGB1 group than in the control (19.11 ± 2.59 vs. 26.82 ± 1.36 μm, P < 0.0001)." (PMID 32275672, 2020). "BMC transplantation reduced post-infarction fibrosis, improved neovascularization, and increased proliferation, while all these effects in repairing the failing myocardium were eliminated by HMGB1-inhibition." (PMID 24204700, 2013). "Neurobehavioral scores, infarction volumes, neuronal apoptosis, and HMGB1 levels were evaluated after reperfusion." (PMID 22277256, 2012). "Since HMGB1 has been shown to induce IL-6 we tested relations between infarction size, IL-6 and HMGB1." (PMID 20090932, 2010). "Recently, it was demonstrated that HMGB1 can induce myocardial regeneration after infarction; injection of HMGB1 into mouse hearts after ischemic damage resulted in the formation of new myocytes by inducing cardiac stem cell proliferation and differentiation." (PMID 17397533, 2007). "Moreover, HMGB1 is negatively related to post-exercise heart rate recovery in post-infarction patients, indicating that HMGB1 was involved in autonomic dysfunction during exercise." (PMID 36376958, 2022). "In addition, intravital imaging revealed that more GFP+/PDGFRα+ cells were recruited to the peri-infarction area in the HMGB1 group than in the control 12 h after treatment." (PMID 32275672, 2020). "Indeed, in the present study, a significant increase in VEGF-A expression was found in the peri-infarction area of the HMGB1 group as compared with the control." (PMID 32275672, 2020). "Thus, targeting the IL6/ADPN/HMGB1 loop may be a novel therapeutic approach for cardiac lymphatic regulation and reduction of cell senescence post-infarction." (PMID 38601146, 2024). "The adipokine, adiponectin, inhibits LPS-induced HMGB1 release in RAW264.7 macrophages and regulates FXR agonism-mediated cardioprotection against post-infarction remodeling and dysfunction." (PMID 38601146, 2024). "Similarly, the exogenous delivery of HMGB-1 has been reported to activate cardiac stem cells, even in the absence of infarction, strengthen the beneficial regenerative contribution of alarmins in physiological conditions." (PMID 33916025, 2021). "Therefore, HMGB1 release may not be a key mechanism for the initial activation of microglia after infarction." (PMID 37062906, 2023).
lymphoma (14 papers, 2011 to 2025). A malignant (clonal) proliferation of B- lymphocytes or T- lymphocytes which involves the lymph nodes, bone marrow and/or extranodal sites. "In a lymphosarcoma model, high mobility group box-1 (HMGB1) levels increased 6 hours after BNCT and decreased at 20 hours." (PMID 40313942, 2025). "Previously, we reported that the level of high mobility group box 1 (HMGB1) was elevated in the xenograft of lymphosarcoma cells in vivo 6 h after neutron irradiation in the presence of BPA in the rat model." (PMID 35336794, 2022). "We have previously reported an early increase in the high mobility group box 1 (HMGB1) protein level in lymphosarcoma-bearing rats in response to BPA-based BNCT." (PMID 35336794, 2022). "After treatment with the HMGB1 inhibitor glycyrrhiza, the invasion and metastatic abilities of lymphoma cells were significantly decreased." (PMID 32660524, 2020). "The results showed that there were significant increases in extracellular HMGB1 levels in lymphoma cells after exposure to normoxic hWJSC-CM (21% O2) or hypoxic hWJSC-CM (5%O2) compared to controls." (PMID 32377203, 2020). "The expression level of HMGB1 in many primary lymphomas is higher than the average level in normal lymph nodes, and HMGB1 is only detected in lymphoma cells." (PMID 32660524, 2020). "In this study, we found that levels of HMGB1 in the plasma of lymphoma-bearing mice were significantly higher compared with the wild-type mice." (PMID 30988279, 2019). "In vivo treatment with EP significantly inhibited DLBCL tumor growth and prolonged survival of lymphoma-bearing mice through inhibition of HMGB1 expression and phosphorylation of Src and ERK1/2." (PMID 30988279, 2019). "Taken together, these findings demonstrate that EP inhibits HMGB1 active release and reduces HMGB1 protein expression in lymphoma-bearing mice." (PMID 30988279, 2019). "The levels of HMGB1 in the plasma of lymphoma-bearing mice were significantly higher compared with wild-type mice." (PMID 30988279, 2019). "In both 40 and 80 mg/kg EP-treated mice, HMGB1 expression in lymphoma tissue was significantly decreased compared with untreated mice." (PMID 30988279, 2019). "HMGB1 expression in DLBCL tumor tissue was significantly decreased in EP-treated lymphoma-bearing mice compared with untreated group." (PMID 30988279, 2019). "ALK-positive lymphoma cells have been shown to release the pro-inflammatory cytokine high-mobility-group box-1 (HMGB-1), which is thought to promote the creation of a “premetastatic niche” within the skin." (PMID 28895885, 2017). "Blood plasma and tumor tissue in lymphoma-bearing mice were collected at the endpoint to determine whether EP could reduce levels of HMGB1 in the plasma and/or alter specific protein expression." (PMID 30988279, 2019). "Besides, extracellular HMGB1 has been shown to act as immune adjuvant by enhancing immunogenicity of apoptotic lymphoma cells and eliciting antibody responses to soluble ovalbumin protein." (PMID 21915243, 2011). "HMGB1-mediated tumor cell proliferation is dependent on phosphorylation of Src and ERK1/2 in lymphoma-bearing mice." (PMID 30988279, 2019). "EP significantly downregulated HMGB1 expression and phosphorylation of Src and ERK1/2 in mice lymphoma tissue." (PMID 30988279, 2019). "HMGB-1 in turn promotes the secretion of IL-8 and MMP-9 by keratinocytes, which result in epidermal inflammation and the invasiveness of ALK+ lymphoma cells, respectively." (PMID 28895885, 2017). "The gene expression level of HMGB1 was upregulated in the lymph nodes of children with Non‐Hodgkin's lymphoma (NHL) compared with normal tissues, and an HMGB1‐positive reaction was only found in lymphoma cells." (PMID 33140586, 2021). "Although, treatment with EP inhibited HMGB1 release in vitro, levels of plasma HMGB1 in EP-treated lymphoma mice were not significantly decreased by comparison with non-EP-treated lymphoma mice." (PMID 30988279, 2019).